FLT3 (fms related receptor tyrosine kinase 3)
Diseases named in the same sentence as FLT3 in open-access papers (continued):
Sharing a sentence is not in itself a finding about the gene and the disease.
acute myeloid leukemia (continued). "Acute myeloid leukemia (AML) patients with a high allelic burden of an internal tandem duplication (ITD)-mutated FMS-like Tyrosine Kinase-3 (FLT3) have a dismal outcome." (PMID 31286998, 2019). "FMS-like tyrosine kinase 3- internal tandem duplication (FLT3-ITD) remains as one of the most frequently mutated genes in acute myeloid leukemia (AML), especially in those with normal cytogenetics." (PMID 31528345, 2019). "Recent studies identified a new cytomorphological feature in AML blasts and found a correlation of the so-called cup-like acute myeloid leukemia with mutations of FLT3 and NPM1." (PMID 31568521, 2019). "Preclinical studies showed that VX-944 was 3 to 40 times more potent than MPA in acute myeloid leukemia (AML) cell lines and was active against both FLT3 mutated and unmutated cells." (PMID 31514446, 2019). "Internal tandem duplication (ITD) mutations in the juxtamembrane domain of FLT3 (FLT3-ITD) are the most frequent kinase mutations in acute myeloid leukemia (AML), occurring in 25–30% of cases." (PMID 29507660, 2018). "A 20-year-old woman with FLT3/ITD mutation-positive relapsed/refractory acute myeloid leukemia (AML) was transferred to our institute in June 2017." (PMID 30334953, 2018). "This study aimed to evaluate DNMT3A exon 23 mutations and their prognostic impacts in the presence of NPM1 and FLT3 mutations in acute myeloid leukemia (AML) patients who underwent allogeneic hematopoietic stem cell transplantation (HSCT)." (PMID 29786546, 2018). "On the basis of the latest reports, when combined with a BH-mimetic, GCS-100 induces apoptosis of acute myeloid leukemia (AML) cells, especially in cases with predominant negative prognostic factors, such as FLT3 ITD mutations." (PMID 29320431, 2018). "The activation of FLT3 through a mutation is recognized as the most common molecular abnormality in acute myeloid leukemia (AML), and these mutations also play a role in other hematologic malignancies." (PMID 29487300, 2018). "In acute myeloid leukemia (AML) the first successes have been in targeting mutations in the receptor tyrosine kinase FLT3." (PMID 29806049, 2017). "More recently, midostaurin (Rydapt), a small molecule inhibitor of VEGF, has been approved for use in acute myeloid leukemia (AML) patients with mutated FMS-like tyrosine kinase inhibitor 3 (FLT3)." (PMID 29285416, 2017). "Around 30% of patients with acute myeloid leukemia (AML) harbor activating mutations in FLT3, a gene normally involved in regulating hematopoiesis." (PMID 28881711, 2017). "Activating mutations of Flt3 are frequently found in acute myeloid leukemia (AML) patients and associated with a poor clinical prognosis." (PMID 28538663, 2017). "FLT3 mutation is found in about 30% of acute myeloid leukemia (AML) patients and is associated with a poor prognosis." (PMID 27331411, 2016). "Internal tandem duplication (ITD) mutations in the Fms-related tyrosine kinase 3 (FLT3) gene (FLT3-ITD) are found in 20–30% of patients with acute myeloid leukemia (AML) and are associated with a poor prognosis." (PMID 27387666, 2016). "In acute myeloid leukemia cells, proteasome inhibitors could reverse the quizartinib resistance induced by FLT3 kinase domain mutations, suggesting that these compounds may prevent the emergence of mutant clones arising from tyrosine kinase inhibitor treatments." (PMID 26934320, 2016). "Similarly, while the impact of FLT3 mutations has been widely explored in acute myeloid leukemia, it is unclear whether FLT3 mutations affect the outcome of ALL patients." (PMID 26883104, 2016). "FLT3 internal tandem duplication (ITD), one of the most frequent mutations in Acute Myeloid Leukemia (AML), is reported to be an unstable marker, as it can evolve from FLT3 ITD- to ITD+ during the disease course." (PMID 26384303, 2015). "More than 30% of acute myeloid leukemia (AML) patients possess activating mutations in the receptor tyrosine kinase FMS-like tyrosine kinase 3 or FLT3." (PMID 25837374, 2015).
acute myeloid leukemia (continued). "We present a unique case of a patient who initially presented with acute myeloid leukemia (AML) with a normal karyotype and FLT3-ITD and NPM1 mutations." (PMID 26798525, 2015). "FLT-3 (FMS-like tyrosine kinase-3) receptor kinase is one of the targets of midostaurin, and its mutations are frequently found in acute myeloid leukemia (AML), which result in the constitutive activation of FLT-3 and induce cell proliferation." (PMID 26141684, 2015). "The deregulated activation of FLT3 due to mutation or overexpression is linked to the progression of acute myeloid leukemia (AML) and is associated with poor prognosis." (PMID 25837374, 2015). "FLT3 expression has been detected in almost all acute myeloid leukemia (AML) patients, and the activating mutations in FLT3 occur in as high as 35% of AML patients and less frequently in acute lymphoblastic leukemia (ALL) patients." (PMID 26046670, 2015). "In acute myeloid leukemia (AML), FLT3 is widely expressed and is mutated in about one third of patients." (PMID 25826077, 2015). "Internal tandem duplications (ITDs) of the gene encoding the Fms-Like Tyrosine kinase-3 (FLT3) receptor are present in approximately 25% of patients with acute myeloid leukemia (AML)." (PMID 26237612, 2014). "Sorafenib induced skin rash has been discussed as a side effect in trials in both, FLT3 wild type and mutated acute myeloid leukemia (AML), as monotherapy or as combination with other chemotherapeutic agents." (PMID 24678393, 2014). "Mutations of FLT3 were first described in 1997 and account for the most frequent molecular mutations in acute myeloid leukemia (AML)." (PMID 24696688, 2014). "FMS-like tyrosine kinase 3 receptor (FLT3) receptor mutations are among the most common somatic mutations in acute myeloid leukemia (AML), with FLT3 internal tandem duplications (ITDs) occurring in 20–35% of adult AML and ∼5–15% of pediatric AML." (PMID 23431389, 2013). "We further demonstrated how de-repression of Flt3 due to the misfolded conformation dependent loss (MCDL) of N-CoR contributed to malignant growth in acute myeloid leukemia (AML)." (PMID 23940660, 2013). "FMS-like tyrosine kinase 3 (FLT3) is a type III RTK expressed in approximately 90% of acute myeloid leukemia (AML) and activating mutations of FLT3 are found in approximately 30% of all AML cases." (PMID 22807997, 2012). "Their work concentrates on the role of mutations in FLT3, a receptor tyrosine kinase, in acute myeloid leukemia (AML)." (PMID 18068625, 2007). "Autophagy induction has recently emerged as a mechanism of resistance to FLT3 inhibitors (FLT3i) in patients with FLT3-ITD mutant acute myeloid leukemia (AML)." (PMID 41876469, 2026). "FMS-like tyrosine kinase 3 (FLT3) mutation is a common prognostic and predictive marker, found in approximately 30% of patients with acute myeloid leukemia (AML)." (PMID 41487332, 2026). "The FLT3-ITD mutation is a critical prognostic marker in acute myeloid leukemia (AML) and recent clinical trials demonstrate that FLT3-based measurable residual disease (MRD) is both prognostic and predictive, guiding therapeutic interventions in intensive and post-transplant settings." (PMID 41828696, 2026). "The clinical success of FLT3 inhibitors has led to their steadily increasing use in the treatment of acute myeloid leukemia (AML), both in the relapsed/refractory setting and as post-transplant maintenance." (PMID 41636849, 2026). "For younger, medically fit patients with NPM1-mutated, FLT3-wildtype acute myeloid leukemia (AML) intensive chemotherapy represents standard of care (SOC), with complete remission (CR) rates observed in up to 85% of patients and 5-year overall survival (OS) rates of 40–50%." (PMID 40629154, 2025). "The FLT3-PI3K-AKT signaling is an established pathway that is constitutively activated in FLT3/ITD acute myeloid leukemia." (PMID 40263296, 2025).
acute myeloid leukemia (continued). "It has important therapeutic significance for AML patients carrying FLT3 internal tandem duplication mutations (FLT3-ITD) and has been approved for the treatment of relapsed/refractory FLT3-mutated acute myeloid leukemia." (PMID 40722724, 2025). "explored inhibition of FLT3 by nemtabrutinib as a potential treatment option of acute myeloid leukemia (AML) in preclinical models." (PMID 41199836, 2025). "PARP inhibitors (PARPi) have shown promise in treating acute myeloid leukemia (AML) and other blood cancers, particularly in cases with specific genetic alterations such as RUNX1-RUNX1T1, PML-RARA, FLT3, and IDH1/2 mutations." (PMID 41048997, 2025). "In acute myeloid leukemia (AML), activating mutations in RTKs such as FLT3 or c-Kit drive sustained PAM signaling, confirmed by hyperphosphorylation of mTORC1 substrates S6K and 4E-BP1 in primary AML samples." (PMID 41356921, 2025). "Despite the use of FMS-like tyrosine kinase 3 (FLT3) inhibitors, outcomes for patients with FLT3-mutated (FLT3mut) acute myeloid leukemia (AML) remain suboptimal because of high rates of relapse." (PMID 41026969, 2025). "Acute myeloid leukemia (AML) with Fms-like tyrosine kinase-3 internal tandem duplication (FLT3-ITD) is strongly correlated with recurrence and poor prognosis." (PMID 40341256, 2025). "FLT3 mutations in acute myeloid leukemia are divided into two major types, FLT3-ITD (internal tandem duplication in the juxta-membrane domain) and FLT3-TKD (point mutations or deletion tyrosine kinase domain)." (PMID 38944027, 2025). "Mutations in FMS-like Tyrosine Kinase 3 (FLT3), such as internal tandem duplications (ITDs), are detected in up to 23% of acute myeloid leukemia (AML) patients and are frequently associated with poor prognosis." (PMID 41463377, 2025). "Owing to the pivotal role of FLT3 in the progression of acute myeloid leukemia, we conducted further investigations into the cellular anti-proliferative effects of FLINs 1–6." (PMID 39963240, 2025). "Adaptive ERK reactivation hinders FLT3 tyrosine kinase inhibitor (TKI) treatment in FLT3/ITD acute myeloid leukemia." (PMID 39395205, 2025). "Midostaurin, is also such an inhibitor, which is mainly utilized in the treatment of acute myeloid leukemia (AML), particularly in patients with FLT3 mutations." (PMID 40455337, 2025). "Cellular assays with human acute myeloid leukemia cells (MV4-11) further confirmed the potential of FLINs 1–6 as FLT3-ITD inhibitors." (PMID 39963240, 2025). "Our study confirms that the targeted inhibition of FLT3-ITD significantly reduces the proliferation of acute myeloid leukemia cells." (PMID 39963240, 2025). "Ko and his team obtained compound 93, which effectively inhibited FLT3 wild-type and FLT3 D835Y mutated genes, showing IC50 values of 0.941 and 0.199 nM, respectively, in acute myeloid leukemia cells." (PMID 40430417, 2025). "The importance of PRMT1 in leukemia has been shown in FLT3-ITD, AML1-ETO, and MLL-EEN-associated acute myeloid leukemia and lymphoid leukemia." (PMID 40801789, 2025). "Acute myeloid leukemia (AML), for example, has over 20 known molecular subtypes, arising from specific genetic alterations such as NPM1 mutations, FLT3-ITD, CEBPA mutations, and various chromosomal rearrangements." (PMID 40940796, 2025). "In acute myeloid leukemia (AML), mutations in the FLT3 gene often lead to aberrant splicing, generating constitutively active forms of the FLT3 receptor tyrosine kinase." (PMID 40563429, 2025). "Kovecses and colleagues reveal that targeted delivery of small activating RNAs restores CEBPA expression in acute myeloid leukemia, enhancing sensitivity to FLT3 inhibition and reducing leukemic burden." (PMID 40686853, 2025).
acute myeloid leukemia (continued). "Background/Objectives: Acute myeloid leukemia (AML) presents significant therapeutic challenges, particularly in cases driven by mutations in the FLT3 tyrosine kinase." (PMID 39861158, 2025). "Fms-like tyrosine kinase 3 (FLT3) has been established as a therapeutic target for acute myeloid leukemia (AML)." (PMID 41471328, 2025). "UNC2025, a small-molecule inhibitor of the MERTK/FLT3 pathway, has demonstrated important antitumor activity against acute lymphoblastic leukemia and acute myeloid leukemia." (PMID 40862051, 2025). "Despite lacking formal approval for myeloid leukemia, sorafenib’s off-label use in FLT3-ITD mutated acute myeloid leukemia (AML) and demonstrated clinical activity in FLT3-wildtype AML have contributed to 2.89% of total publications in this domain." (PMID 40771926, 2025). "In Fms‐like receptor tyrosine kinase 3 (FLT3)‐ITD mutant acute myeloid leukemia (AML), PRMT1 expression is markedly elevated." (PMID 41256732, 2025). "Acute myeloid leukemia (AML) progression is significantly influenced by Feline McDonough Sarcoma (FMS)-like tyrosine kinase 3 (FLT3) signaling, while Wilms’ tumor 1 (WT1) serves as a key prognostic marker." (PMID 40361130, 2025). "Since compounds 1−5 exhibited cytotoxic effects against FLT3-driven acute myeloid leukemia cells such as MOLM-13 and MV-4-11, they were tested in a cell-free assay to evaluate FLT3 kinase inhibition." (PMID 41286812, 2025). "In acute myeloid leukemia (AML), a different spectrum of targeted therapies has emerged, particularly for patients with FLT3 mutations." (PMID 41228293, 2025). "FLT3-ITD is a common driver mutation that manifests as a high leukemic burden and leads to poor prognosis in patients with acute myeloid leukemia." (PMID 39758420, 2024). "A previous study revealed that GATM functions as a downstream factor in promoting the progression of FLT3‐ITD‐mutant acute myeloid leukaemia by regulating de novo creatine biosynthesis." (PMID 39160643, 2024). "Tyrosine kinase inhibitors (TKIs) targeting fms-like tyrosine kinase 3 (Flt3) such as quizartinib were specifically designed for acute myeloid leukemia treatment, but also multi-targeting TKIs applied to solid tumor patients inhibit Flt3." (PMID 37945814, 2024). "A previous study demonstrated that the upregulation of miR-155 regulates c-myc reduction in human FLT3-wildtype acute myeloid leukemia (AML)." (PMID 39314840, 2024). "Quizartinib has been approved for newly diagnosed acute myeloid leukemia that is FLT3 internal tandem duplication-positive." (PMID 38530400, 2024). "Mutations in nucleophosmin 1 (NPM1), FMS-like tyrosine kinase 3 (FLT3) and CCAAT/enhancer-binding protein α (CEBPA) contribute to risk stratification of cytogenetically normal acute myeloid leukemia (CN-AML)." (PMID 39767827, 2024). "FLT3-activating mutations are commonly found in Acute Myeloid Leukemias (AML), accounting for approximately one-third of adult AML cases and 10%–15% of pediatric AML cases." (PMID 39711880, 2024). "Bimiralisib has also been shown to have efficacy in combination with BCL2 (B-cell lymphoma 2) inhibitor venetoclax in acute myeloid leukemia (AML) with IDH2, NPM1, and FLT3 mutations in preclinical studies." (PMID 38396649, 2024). "Acute myeloid leukemia (AML) with an internal tandem duplication in the fms‐like tyrosine kinase receptor 3 gene (FLT3‐ITD) is associated with poor survival, and few studies have examined the impact of modifiable behaviors, such as nutrient quality and timing, in this subset of acute leukemia." (PMID 38334474, 2024). "The FMS‐like tyrosine kinase 3 (FLT3) domain is the most mutated gene in acute myeloid leukemia (AML), with FLT3 internal tandem duplication (ITD) mutations conferring adverse outcomes." (PMID 38633126, 2024). "In a similar manner, pacritinib has been shown to have activity in acute myeloid leukemia cells with drug resistance to FLT3 therapy because of its combined JAK2/FLT3 activity." (PMID 38374336, 2024).
acute myeloid leukemia (continued). "Most of the knowledge on FLT3 implications comes from the study of acute myeloid leukaemia and so far, few studies have been performed in other leukaemias." (PMID 38049555, 2024). "A 65-year-old woman was diagnosed with acute myeloid leukemia (AML-M2a subtype) on July 18, 2023,accompanied by mutations in FMS‐like tyrosine kinase 3 (FLT3)-ITD, NPM1, TET2, EZH2, and other genes." (PMID 39544304, 2024). "In conclusion, FLT3-positive acute myeloid leukemia remains an extremely aggressive disease that requires timely treatment and the optimization of the use of new drugs at our disposal to minimize the emergence of resistance." (PMID 39199635, 2024). "They provided evidence from cBioPortal annotations to show that the FLT3 gene had the highest frequency of copy number alterations among 1438 CRC patients aged 18 to 48 years old with concomitant acute myeloid leukemia (AML)." (PMID 39195204, 2024). "Activating mutations of FLT3, including Internal Tandem Duplication (FLT3-ITD), are associated with poor prognosis for acute myeloid leukemia (AML) patients." (PMID 38495876, 2024). "One of the prevalent genetic abnormalities in acute myeloid leukemia is the Internal Tandem Duplication of FLT3 gene, known as FLT3-ITD." (PMID 38909325, 2024). "In the phase I study (NCT03552029), patients were enrolled to milademetan plus quizartinib combination study in FLT3-ITD mutant acute myeloid leukemia (AML)." (PMID 38481290, 2024). "Gilteritinib, an orally available second-generation FMS-like tyrosine kinase 3 (FLT3) inhibitor, is approved by the FDA for the treatment of relapsed or refractory acute myeloid leukemia (AML) harboring FLT3 mutation in 2018." (PMID 39349433, 2024). "A notable number of these studies, 44% (10/23), were centered on rare blood‐related cancers identified by distinctive genetic markers, such as FLT3+ in acute myeloid leukemia and the Philadelphia chromosome in acute lymphoblastic leukemia." (PMID 38984669, 2024). "Over 30-35% of patients suffering from acute myeloid leukemia are due to mutations of FLT3‐ITD and FLT3‐TKD, consequently resulting in prolonged activation of protein that promotes cell proliferation and survival." (PMID 38344573, 2024). "In particular, low specificity does not preclude clinical approval, as exemplified by Midostaurin, a broad-spectrum CKI that is approved for treatment of FLT3+ acute myelogenous leukemias." (PMID 38724853, 2024). "In FLT3-ITD acute myeloid leukemia, the combination of homoharringtonine and quizartinib AKT and its downstream targets, including c-MYC, reduces the ABCG2 overexpressing side population." (PMID 38255216, 2024). "Internal tandem duplication of the fms-like tyrosine kinase 3 receptor tyrosine kinase (FLT3-ITD) is present in acute myeloid leukemia (AML) in 30% of patients." (PMID 38284896, 2024). "Samples from patients with acute myeloid leukaemia (AML) exhibit dysregulated Fyn expression, which is linked to both oncogenic FLT3-ITD and wild-type FLT3." (PMID 39697541, 2024). "For example, circ-MYBL2, a circRNA from MYBL2 gene, is reported to facilitate the progression of acute myeloid leukemia by regulating fms-related receptor tyrosine kinase 3 (FLT3) translation through recruiting polypyrimidine tract binding protein 1 (PTBP1)." (PMID 38165465, 2024). "Approximately 30% of acute myeloid leukemias are genetically defined by alteration in the FMS-like tyrosine kinase 3 (FLT3)." (PMID 39518156, 2024). "Apart from FLT3, there are some other recurrent genetic alterations that are also found in other acute myeloid leukemia subtypes, including WT1 (14%), NRAS (10%), KRAS (4%) and MYC amplification (12%)." (PMID 38921185, 2024). "FLT3 is frequently hyperactivated in acute myeloid leukemia (AML) which represents one-third of leukemia cases worldwide." (PMID 39300221, 2024).